SPDYE8 (speedy/RINGO cell cycle regulator family member E8)
Synonyms: SPDYE8P
Tractability: No criterion of Open Targets' tractability assessment is met for any kind of drug.
Gene: Protein-coding gene on chromosome 7 (73,019,719 to 73,029,766, reverse strand). Ensembl gene ENSG00000273520.
Gene Ontology:
Molecular function: protein kinase binding
Homologues: Orthologues: rat Spdye4 (49% identical), mouse Spdye4a (48% identical), mouse Spdye4b (44% identical). Paralogues in human: SPDYE10 (100% identical), SPDYE11 (100% identical), SPDYE17 (100% identical), SPDYE9 (100% identical), SPDYE13 (99% identical), SPDYE14 (99% identical), SPDYE15 (99% identical), SPDYE12 (99% identical), SPDYE3 (89% identical), SPDYE18 (83% identical), SPDYE16 (83% identical), SPDYE2 (83% identical), and 6 more.